DIPK1B (divergent protein kinase domain 1B)
Synonyms: C9orf136; FAM69B; PP6977; MGC20262
Tractability: Antibody: UniProt predicts a signal peptide or a membrane-spanning region. PROTAC: ubiquitination databases record sites on it.
Gene: Protein-coding gene on chromosome 9 (136,712,468 to 136,724,742, forward strand). Ensembl gene ENSG00000165716.
Subcellular location: Endoplasmic reticulum membrane
Subcellular location (Human Protein Atlas): Nuclear bodies; Nucleoplasm; Vesicles
Gene Ontology:
Molecular function: protein binding
Cellular component: endoplasmic reticulum membrane
Genetic constraint (gnomAD): Loss-of-function variants: 16 observed, 20.01 expected, observed/expected ratio (o/e) 0.8, 90% interval 0.54 to 1.22. The synonymous counts are far from expectation, so gnomAD's model fits this gene poorly and the ratio says little. Missense variants: 627 observed, 566.28 expected, observed/expected ratio (o/e) 1.11, 90% interval 1.04 to 1.18. Synonymous variants: 334 observed, 254.15 expected, observed/expected ratio (o/e) 1.31, 90% interval 1.2 to 1.44.
Homologues: Orthologues: chimpanzee DIPK1B (99% identical), macaque DIPK1B (99% identical), mouse Dipk1b (89% identical), dog DIPK1B (89% identical), guinea pig DIPK1B (88% identical), pig DIPK1B (87% identical), rat Dipk1b (85% identical), tropical clawed frog dipk1b (62% identical), zebrafish dipk1b (62% identical), tropical clawed frog dipk1b (42% identical), Caenorhabditis elegans C53D5.1 (21% identical), Drosophila melanogaster aln (19% identical). Paralogues in human: DIPK1A (47% identical), DIPK1C (23% identical).
Diseases named in the same sentence as DIPK1B in open-access papers:
DIPK1B is named in the same sentence as 3 diseases in open-access papers, as found by Europe PMC text mining. Sharing a sentence is not in itself a finding about the gene and the disease.
DIPK1B shares sentences with these, for which no sentence is quoted: autism (1 paper); autism spectrum disorder (1); neurological disorders (1).